REN (renin)
Diseases named in the same sentence as REN in open-access papers (continued):
Sharing a sentence is not in itself a finding about the gene and the disease.
tumor (continued). "Immunohistochemically, the tumor cells showed strong positivity for renin but were negative for cytokeratin and epithelial membrane antigen." (PMID 23607027, 2013). "The renin–angiotensin system (RAS) is thought to have a role in carcinogenesis, and RAS inhibition may prevent tumour growth." (PMID 20978506, 2010). "Renin-secreting tumours of several nonrenal origins have been described and the role of the RAS has been evaluated in a few situations in human cancer." (PMID 14997208, 2004). "Our Elisa results showed significantly lower PRA concentrations in renal tumor tissue compared to normal kidney tissue surrounding the tumor, suggesting that renin removal from the renal tumor may not be a major factor in BP reduction in hypertensive patients." (PMID 40959573, 2025). "Renin-secretory tumor could not explain her vascular abnormalities in the spleen or pancreas, and there was no identified mass on abdominal pelvic CTA to support a renin-secreting tumor." (PMID 38165475, 2024). "The underlying mechanism is complex and could be explained by an increased plasma renin activity and aldosterone levels in the peripheral blood despite the absence of renal artery stenosis or a renin-producing tumor." (PMID 36553431, 2022). "However, we did not measure the concentrations of renin, angiotensin I, angiotensin II, and aldosterone during surgery before or after tumor resection." (PMID 32056027, 2020). "Tumor cell-derived lactate, rather than the drop of pH values in hypoxic conditions has an important signaling role in inducing Ang II generation by activating expression of renin and chymase in hypoxic tumor cells." (PMID 28205588, 2017). "This case report aims to not only describe a physiologically, medically, and surgically interesting and rare tumor, but also to place ectopic renin‐secreting tumors on the differential diagnosis when presenting with elevated plasma renin activity (PRA), low aldosterone, and negative catecholamines." (PMID 26997629, 2016). "Immunohistochemically, the tumor cells are positive for renin, but negative for epithelial markers." (PMID 23607027, 2013). "Some investigators suggest that renin synthesis and storage may be concordant, whereas others consider that the positivity of messenger RNA in the tumor cytoplasm may be due to uptake of renin rather than renin production." (PMID 21871063, 2011). "Hence, it is tempting to speculate that the anti-tumor properties of ACE inhibitors might not be exclusively mediated by impairment of the renin-angiotensin system axis, but in fact may also involve the kallikrein-kinin system axis." (PMID 23691222, 2013). "The production of renin and AGT or a potential function of renin, angiotensins and/or AGT in these tumours was not evaluated in these previous experiments." (PMID 14997208, 2004).
infection (67 papers, 2009 to 2026). The state of being infected such as from the introduction of a foreign agent such as serum, vaccine, antigenic substance or organism. "Patients with pre-existing HF are particularly susceptible to this infection due to the negative regulatory role of ACE-2 in the activation of the renin–angiotensin–aldosterone system (RAAS)." (PMID 40094849, 2025). "It plays a regulatory role in the immune system and moderates the renin–angiotensin system, which is implicated in infection pathogenesis." (PMID 36558489, 2022). "Inhibition of the renin-angiotensin system increases the susceptibility of primary hepatocytes to infection with pseudotyped viral particles." (PMID 35978143, 2022). "Age and gender did not contribute substantially to infection risk, but did so for the risk of severe disease Co-morbid health conditions, especially those affecting renin-angiotensin system, had an impact on both the risk of infection and severe disease course." (PMID 35709192, 2022). "Demographic and clinical comorbidities associated with the severity of infection suggest that possible variants known to influence the renin–angiotensin–aldosterone (RAAS) system pathway (particularly those that influence ACE2) may contribute to the heterogenous infection response." (PMID 32501190, 2020). "This interaction induces ACE2 downregulation upon infection of alveolar cells, disrupting the renin-angiotensin system (RAS) balance and overactivating the ACE-Ang II axis." (PMID 41012594, 2025). "Both Il22−/− and Il22+/+ mice showed elevated serum renin and corticosterone following infection; however, increases were greater in Il22−/− mice, and FT resulted in significantly lower levels compared to untreated mice." (PMID 41361166, 2025). "The rapid replication of the novel coronavirus in the human body after infection leads to the overactivation of T cells, immune dysfunction, systemic inflammatory reactions, and dysfunction of the renin-angiotensin system (RAS)." (PMID 38145047, 2023). "Tissue and circulating renin‐angiotensin systems (RASs) play an essential role in the host response to infection and injury because of the actions of Ang II, mediated via its AT1 receptor." (PMID 35106954, 2022). "The SARS-CoV-2 infection is initiated as virus binding to angiotensin-converting enzyme 2 (ACE2), which is highly expressed in the heart, resulting in direct infection and dysregulation of the renin-angiotensin system (RAS)." (PMID 35600485, 2022). "The balance of the Renin-Angiotensin System (RAS) components plays a crucial role in determining the outcome of the infection." (PMID 36137134, 2022). "Despite ACE2 serving as the portal for infection, the continuation of clinically indicated renin-angiotensin-aldosterone blockers is recommended according to the present evidence." (PMID 32624690, 2020). "When inspecting the quantitative data for other proteins in the renin-angiotensin system, two other proteins were found to be down-regulated 24 h post-infection, namely cathepsin A (CTSA) and angiotensinogen (AGT)." (PMID 32575076, 2020). "Despite angiotensin-converting enzyme 2 serving as the portal for infection, the continuation of clinically indicated renin-angiotensin-aldosterone blockers is recommended according to the present evidence." (PMID 32624690, 2020). "This study has also demonstrated the role of renin in the leukocyte recruitment during inflammatory process and/or infection." (PMID 31333451, 2019). "The reason for this might be that the patients with HT have renin–angiotensin system abnormalities and are more prone to severe infection, and the antibody responses in these individuals may be variable." (PMID 40141774, 2025). "Additionally, the inhibition of the renin-angiotensin system increases the infection ratio of both human and mouse hepatocytes." (PMID 35978143, 2022).
infection (continued). "The renin-angiotensin framework that intervened with these impacts in animal testing has specific importance regarding extreme infection with SARS-CoV-2, in which the renin-angiotensin system was found to be overactive, resulting in a dismal or unfavorable prognosis." (PMID 35444872, 2022). "Fifth, the serum levels of ACE, angiotensinogen, angiotensin 1–7, chymase, and the other enzymes of the renin-angiotensin system were not measured in the patients of this cohort, and thus their associations with the risk of infection were not evaluated." (PMID 35155493, 2022). "However, DPP-4i users were more frequently under renin-angiotensin-aldosterone system blockers and, upon admission, appeared to have a slightly more severe form of infection, with higher plasma glucose and C-reactive protein (CRP) concentrations." (PMID 36289885, 2022). "Our results do not support the hypothesis that modulators of the angiotensin–renin system may increase the infection with SARS-CoV-2 via increased ACE2 expression." (PMID 34440554, 2021). "It was hypothesized that modulators of the angiotensin–renin system increase the infection with SARS-CoV-2 via increased ACE2 expression, since SARS-CoV-2 entry into cells depends on ACE2." (PMID 34440554, 2021). "In contrast, infection with cytomegalovirus enhances renin and Ang II activities, which in turn triggers RAAS, subsequently elevating BP, may imply the complexity of the biology of BP regulation and infectious disease." (PMID 30636949, 2019). "Cells with mock infection only had a basal level expression of renin." (PMID 19436702, 2009). "Moreover, Renin positively correlated with lymphocytes, consistent with reports of a unique lymphocyte population that may produce Renin to protect against infection, raising the question of whether this is an adaptive response that may occur in CKD/ESKD71." (PMID 38040779, 2023). "Thus, the RAAS (renin‐angiotensin aldosterone system) can be seen as an integrated system acting at both the cellular level and as an endocrine system coordinating the whole‐body response to injury/infection." (PMID 35106954, 2022). "It was postulated that chronic exposure to these infections could have either triggered the pro-inflammatory cascade, or conferred oxidative stress to the circulation, thus enhancing the renin-angiotensin-aldosterone system (RAAS) which in turn elevated the BP." (PMID 30636949, 2019). "However, it has been described that the expression of both receptors is increased under pathological conditions related to oxidative stress, pro-inflammatory stimuli (e.g., inflammation and infection) as well as vasoactive peptides of the renin-angiotensin system." (PMID 30890928, 2019). "We infected As4.1 cells by MCMV in differing multiplicities of infection (MOI), and detected renin expression by immunofluorescent microscopy." (PMID 19436702, 2009). "When UV-inactivated MCMV was employed as a control in the infection, no increase in renin expression was detected (data not shown)." (PMID 19436702, 2009). "Consistent with the findings of the mouse trial, human CMV (HCMV) infection of blood vessel endothelial cells (EC) induced renin expression in a non-lytic infection manner." (PMID 19436702, 2009).
heart disease (40 papers, 2013 to 2026). "More than 75% of patients with ischaemic heart disease were taking an antithrombotic or a lipid-lowering agent and more than 50% were taking an agent acting on the renin-angiotensin system." (PMID 41667178, 2026). "For ICH, IVW identified four categories (agents acting on the renin-angiotensin system, vasodilators used in cardiac diseases, diuretics, and calcium channel blockers) significantly associated with ICH, as the figure shows." (PMID 37020515, 2023). "We should ensure that patients who are suffering from heart disease receive these drugs when indicated in order to improve the function of their renin-angiotensin-aldosterone system or thrombogenic status." (PMID 36675633, 2023). "The cardioprotective role of ADM against cell death in heart diseases is through disruption of mitochondrial metabolism and by reducing renin–aldosterone system levels, thereby improving cardiac output and vascular smooth muscle resistance." (PMID 35205232, 2022). "Among the mechanisms by which nicotine, and its major metabolite, cotinine, contribute to heart disease is the renin‐angiotensin‐aldosterone system (RAAS) activation." (PMID 31236278, 2019). "Chymase in the renin–angiotensin system (RAS) actively contributes to cardiac disease progression." (PMID 38612317, 2024). "Our results suggest that the renin-angiotensin system might play an important role in the development of cardiac diseases induced by PG-LPS." (PMID 37983238, 2023). "In relation to heart disease, one of the phases of viral action is the inhibition of the Angiotensin 2-Converter enzyme (ECA-2), which could deregulate the renin-angiotensin-aldosterone system, causing local and systemic tissue lesions." (PMID 36901646, 2023). "The renin-angiotensin-aldosterone system (RAAS) is implicated in the modulation of almost all physiological cardiac functions and is also involved in the development and progression of cardiac diseases." (PMID 24478712, 2013). "Angiotensin-converting enzyme inhibitors (ACEI) such as benazepril are commonly prescribed in both humans and dogs with heart disease to mitigate the renin–angiotensin–aldosterone system (RAAS); however, the dose-dependent effects of benazepril on comprehensive RAAS components remain unknown." (PMID 36792677, 2023). "Consistently, RNA-seq analysis revealed that key cardiac disease-related signaling pathways, including TGFβ, IL6, Renin-Angiotensin, and NFAT, were blunted in SIRT5OE TAC mice." (PMID 35851833, 2022). "The role of the brain renin-angiotensin II system (RAS) in modulating sympathetic outflow and baroreflex sensitivity in heart disease is well established." (PMID 25006809, 2014). "The renin-angiotensin system (RAS) has a prominent role in the physiological functions of cardiovascular system and in the pathophysiology of heart diseases such as CAD." (PMID 25984491, 2014). "Of interest for our study, previous work showed that AMPK regulates the renin-angiotensin system, and the observed alteration of AMPK signaling in CS could also participate in the cardiac disease through this system." (PMID 35230976, 2022). "Lastly, data from patients undergoing long-term treatment for heart disease with statins, renin/angiotensin blockers, and beta-blockers were not included in the protocol for this study." (PMID 36158802, 2022).
metabolic disorders (36 papers, 2013 to 2025). "Additionally, metabolic disorders that occur parallel to genes encoding expression may be involved in the altered adrenergic and renin-angiotensin-aldosterone compound system, oxidative stress, and inflammatory tissue deregulation." (PMID 36353510, 2022). "ACE, a central component of the renin–angiotensin system, links cardiovascular regulation with metabolic disorders." (PMID 41464892, 2025). "Aldosterone plays important parts in development of cardio-metabolic diseases as end product of renin-angiotensin-aldosterone system." (PMID 38773424, 2024). "Metabolic disorders can activate renin-angiotensin-aldosterone system (RAAS), increase angiotensin II and aldosterone activity, which leads to cardiomyocyte hypertrophy, increased cardiac fibroblast proliferation and myocardial remodeling acceleration." (PMID 39525850, 2024). "ACE2 is a regulatory enzyme of the renin-angiotensin system and has protective functions in many cardiovascular, pulmonary and metabolic diseases." (PMID 33057007, 2020). "The role of ACE2 variants in cardiovascular and metabolic diseases may be due to decreased ACE2 amount and expression, which increases inflammation and tissue injuries caused by unmetabolized angiotensin II and an unbalanced renin–angiotensin–aldosterone system." (PMID 37521828, 2022). "The renin-angiotensin system (RAS) is important in the onset and course of cardiovascular, kidney, and metabolic disorders." (PMID 32999396, 2020).
retinopathy (13 papers, 2011 to 2024). "Prorenin, the precursor of renin is highly elevated in ocular fluid of diabetic patients with proliferative retinopathy." (PMID 24968134, 2014). "The high level of renin and ACE in diabetic patients could lead to an excess of angiotensin II in the eyes, and elevate local intravascular blood pressure to hasten the development of retinopathy." (PMID 29484134, 2018).
neurodegenerative disease (12 papers, 2011 to 2026). A disorder of the central nervous system characterized by gradual and progressive loss of neural tissue and neurologic function. "Finally, the (pro)renin/PRR axis has been described after discovery of the existence of the renin receptor (PRR), which acts independently of the classical axis after activation by renin itself and its precursor, (pro)renin and it has been linked to cardiovascular, renal and degenerative diseases." (PMID 33114706, 2020). "Candesartan inhibition of their proinflammatory effects stresses the importance of tissue Renin–Angiotensin Systems intertwined in metabolic and neurodegenerative diseases." (PMID 40722297, 2025). "Recently, central renin–angiotensin system (RAS) has been involved in the pathogenesis of several neurodegenerative diseases such as PD, AD, and HD." (PMID 35002694, 2021). "Evidence from studies in HD animal models links the renin–angiotensin system (RAS) to the pathophysiology of neurodegenerative diseases." (PMID 28596754, 2017). "The renin–angiotensin system (RAS) is a potential contributor to the pathophysiology of neurodegenerative diseases." (PMID 28596754, 2017). "These renin inhibitors are therefore potential therapeutic agents for the treatment of hypertension and related cardiovascular diseases, and their subsequent effects in the initiation and evolution of neurodegenerative diseases." (PMID 37765259, 2023). "Various reports indicate the detrimental involvement of the brain renin–angiotensin system (RAS) in oxidative stress, neuroinflammation, and apoptosis in various neurodegenerative diseases." (PMID 34827667, 2021).
vasculopathy (12 papers, 2014 to 2025). "Angiotensin II acts as a peptide hormone and component of renin-angiotensin- system (RAS) regulating the blood pressure, and seems to be involved in renal and vascular disorders." (PMID 25505856, 2014).
inflammation (11 papers, 2013 to 2024). Aberrant reaction of the microcirculation characterized by movement of fluid and leukocytes from the blood into extravascular tissues. "Despite initial fears, evidence from retrospective observational studies supports the inhibition of the renin-angiotensin system as an emerging pathway to delay or moderate angiotensin II-driven lung inflammation." (PMID 33854432, 2021). "Studies have also found that the renin-angiotensin-aldosterone system (RAAS) can be activated by UA partly through the MAPK pathway, contributes to the increased release of cytokines and induces atrial inflammation." (PMID 38913677, 2024).
kidney (11 papers, 2013 to 2024). "Impaired kidney function activates the renin-angiotensin-aldosterone system (RAAS), causing the kidneys to produce vasoactive hormones which raise blood pressure." (PMID 34067580, 2021). "In addition, a decrease in cardiac output in end-stage HF results in poor kidney perfusion, reduced renal autoregulation, increased renin–angiotensin system activation, and renal arterial vasoconstriction, which consequently further leads to kidney dysfunction." (PMID 34829684, 2021). "In the presence of kidney injury, elevated beta-catenin levels lead to fibrosis due to the increased activation of various beta-catenin dependent pathways involved in the fibrotic response, such as the Wnt signaling pathway, the renin-angiotensin system, and Tgfb1/Smad pathway." (PMID 32555682, 2020). "Similarly, renin-angiotensin-aldosterone system inhibitors or other drugs that affect the GFR may result in small changes in serum creatinine levels that are not indicative of kidney injury." (PMID 35677313, 2022).
endocrine disorder (4 papers, 2020 to 2026). "Specific factors that intervene to favor this imbalance are metabolic acidosis, endocrine disorders involving the insulin/IGF-1 signaling, low testosterone levels, alterations in the renin–angiotensin–aldosterone system, systemic inflammation, and an abnormal hypothalamic appetite regulation." (PMID 34383112, 2022).
genetic disorder (4 papers, 2023 to 2025). "Autosomal Recessive Renal Tubular Dysgenesis (AR-RTD) is a fatal genetic disorder characterized by complete absence or severe depletion of proximal tubules (PT) in patients harboring pathogenic variants in genes involved in the Renin–Angiotensin–Aldosterone System." (PMID 38071212, 2023).
infectious disease (4 papers, 2021 to 2022). A disorder directly resulting from the presence and activity of a microbial, viral, or parasitic agent in humans. "The renin–angiotensin system (RAS) plays a vital role in multiple infectious diseases through augmenting inflammatory reactions." (PMID 34220748, 2021). "However, pleiotropic effects on renin-angiotensin system regulation and infectious disease reduction have been reported." (PMID 34787531, 2021).